AFP (alpha fetoprotein)
Diseases named in the same sentence as AFP in open-access papers (continued):
Sharing a sentence is not in itself a finding about the gene and the disease.
tumor (continued). "Other prognostic factors have been revealed, such as an AFP level of 100 ng/ml or greater, bone metastasis, three or more tumors, and tumor size at the time of recurrence." (PMID 32466780, 2020). "Univariate analysis showed that high circulating neutrophil percentage, γ-glutamyltransferase (GGT), pretreatment serum AFP status, ascites, tumor diameter, portal vein invasion and metastasis were potential influence factors for OS." (PMID 32328178, 2020). "Respectively, the cut-offs were 80ng/mL, 4000ng/mL for AFP; 50U/L, 75U/L, 135U/L for γ-GT; and 5cm for major tumor size." (PMID 32489476, 2020). "The present study demonstrated that FPR and GPR were correlated with AFP-NHCC as well as tumor size and BCLC stage." (PMID 32190001, 2020). "Tumor size and AFP level reflect tumor burden in our model, and were also included in previous prediction models such as ABCR and HAP score." (PMID 32487089, 2020). "Changes in tumor marker (alpha-fetoprotein (AFP)/des-gamma-carboxy prothrombin (DCP)) levels and albumin–bilirubin (ALBI) score between the baseline value and that estimated one month after treatment were evaluated." (PMID 32218295, 2020). "These criteria are termed the 5‐5‐500 rule and are as follows: maximum tumor size within 5 cm, within five tumor nodules, and AFP within 500 ng/mL." (PMID 32724885, 2020). "There are three serum tumor markers currently used for TGCT: Alpha-fetoprotein (AFP), human chorionic gonadotropin (HCG) and lactate dehydrogenase (LDH)." (PMID 31851466, 2020). "AUROC was calculated to determine the optimal cut-off values of AFP, γ-GT and the major tumor size, to establish an easy-to-use prediction model and simultaneously maintain its discrimination efficacy." (PMID 32489476, 2020). "AFP level is commonly used to estimate the severity of tumor burden and as a prognostic measure for the response to different treatments." (PMID 32426129, 2020). "The median tumor size was 31 mm (range, 10–170 mm), and the median alpha-fetoprotein level was 32.1 ng/mL (range, 1.5–118,660 ng/mL)." (PMID 32325921, 2020). "We observed that the group of E+/+ patients was distinct from E+/− and E−/− patients in the context of tumor aggressiveness (serum AFP-levels (</≥400 ng/mL) and number of HCC nodules)." (PMID 33225916, 2020). "Tumour number ≥ two (HR 1.54), alpha-fetoprotein > 400 μg/l (HR 1.14), serum albumin < 3.6 g/dl (HR 1.63) and total bilirubin > 0.9 mg/dl (HR 1.58) contributed significantly in Cox proportional hazards regression (each p < 0.05)." (PMID 32125515, 2020). "In the multivariate analysis, tumor size, AFP < 100 ng/mL and serum alkaline phosphatase were independent factors for survival following DEB-TACE-1." (PMID 32487071, 2020). "In accordance with published studies, our study showed that the age (>60 years), tumor size (>5 cm), AFP level (>400 ng/ml), ALT level (>40 U/l), and BCLC stage were linked with higher risk of death after hepatectomy." (PMID 32478394, 2020). "The tumor markers alpha fetoprotein (AFP), carcinoembryonic antigen (CEA), carbohydrate antigen 125 (CA125) and carbohydrate antigen 19–9 (CA19–9) were in the normal range, and no acid-fast bacilli were found in sputum smears." (PMID 32962678, 2020). "Preoperative tumor marker levels were as follows: α-fetoprotein (AFP), 5 ng/ml; and des-ɤ-carboxy prothrombin (DCP), 327 mAU/ml." (PMID 32466780, 2020). "All tumor markers (carcinoembryonic antigen, squamous cell carcinoma antigen, alpha-fetoprotein, and carbohydrate antigen 19-9) were within the respective normal ranges." (PMID 31960152, 2020). "The sensitivities of AFP ≥ 400 ng/ml, tumor diameter ≥ 5 cm, preoperative CTC ≥ 5 and multiparameter combination were 44.8, 50.0, 91.4, and 91.4%, respectively, and the specificities were 82.3, 70.9, 79.7, and 79.7%." (PMID 33129301, 2020). "The tumor index AFP is principally used for hepatocarcinoma testing, and the pattern of model 2 (with PLA variants) suggested that this indicator is unnecessary for CRC prediction." (PMID 32455870, 2020).
tumor (continued). "All possible information on tumor biology (AFP lab trends, tissue biopsies) should be obtained and discussed in a multi‐disciplinary setting." (PMID 32490334, 2020). "Several factors related to HCC recurrence were identified in previous models, including maximum tumor diameter, tumor number, portal vein invasion, and serum tumor markers such as alpha-fetoprotein (AFP) and protein induced by vitamin K absence-II (PIVKA-II)." (PMID 33003306, 2020). "The positive expression rates of GPC3, CK8, CK19, β-catenin, and AFP in the tumor tissue of these 42 patients were 100% (42/42), 88.1% (37/42), 92.9% (39/42), 92.9% (39/42), and 64.3% (27/42), respectively." (PMID 32195259, 2020). "But both miR-21 and AFP ratio were equally capable of discriminating CR from other tumor responses and can be used as an independent predictor." (PMID 33614488, 2020). "Up-regulation of circSMYD4 inhibited the proliferation, invasion and migration and promoted the apoptosis of HCC cells in vitro, while it inhibited tumor growth, promoted apoptosis-related proteins, and suppressed alpha-fetoprotein (AFP) levels in vivo." (PMID 33292243, 2020). "Successful DS as evidenced by tumor shrinkage or a drop in AFP serves as a surrogate for good tumor biology, and allows LT to be considered in these patients." (PMID 33553240, 2020). "An approach to the TT diagnosis is based on ultrasonographic findings, clinical and endocrinological data and tumour marker levels as alpha-phetoproteine (AFP), beta-human gonadotropin chorionic (B-HCG), lactate dehydrogenase (LDH) or testosterone." (PMID 32462465, 2020). "The multivariate analysis showed that elevated serum alpha-fetoprotein levels (≥20 ng/ml) and decreased expression of SVEP1 in tumor tissues were two independent risk factors for the prognosis of HCC." (PMID 32371982, 2020). "Meanwhile, the AUC value of the combination of FPR and GPR in AFP-NHCC patients with tumor size < 3 cm was 0.943 (95% CI = 0.906–0.969), while the sensitivity and specificity was 87.50% and 86.93%, respectively." (PMID 32190001, 2020). "The main points of this paper are that the up-to-seven criteria (the combination of tumor size and number), AFP level as malignant potential, and albumin level as liver function can be used to select patients with intermediate HCC for HR." (PMID 33112547, 2020). "A CTC count greater than or equal to 5 had better predictive value than AFP > 400 μg/L and tumor diameter > 5 cm." (PMID 33129301, 2020). "Serum tumor marker levels were normal (alfa-fetoprotein [AFP]: 11.25 ng/mL, beta-human chorionic gonadotropin [beta-HCG]: <0.10 mg/mL), although serum CA125 levels were not measured." (PMID 32957389, 2020). "Tumor markers are widely used to screen for HCC in high-risk patients; these include α-fetoprotein (AFP) and protein induced by vitamin K absence or antagonists-II (PIVKA-II)." (PMID 33171811, 2020). "The comparison between low and high AFP of tumor samples also showed that 98.7% of proteins varied within 2-fold." (PMID 32426269, 2020). "While vital for the developing fetus, the role of AFP in adult tissues is less well-understood but appears dispensable, thus making it a promising tumor antigen for T cell-based immunotherapies." (PMID 32425926, 2020). "One widely used model in HCC is the Metroticket model, which captures a variety of pre-LT features of HCC that are indicative of disease biology and aggressiveness, such as alpha-fetoprotein, tumor size, and tumor number." (PMID 33202588, 2020). "Multivariable analysis of preoperative factors that were prognostically significant in the univariable analyses showed that the LSG, ICGR15, AFP, and tumor size were significant." (PMID 33272298, 2020). "Patients with high serum AFP usually have large tumours, multiple diffuse tumours, portal vein thrombosis, enhanced infiltration and increased metastasis." (PMID 33090723, 2020).
tumor (continued). "Although serum tumor markers like AFP, CEA and PSA have been extensively studied and used in the clinic, questions regarding the mechanisms leading to their expression in cancer have not been well answered." (PMID 31897235, 2020). "As expected, it was found that overexpression of circSMYD4 targeted the inhibition of miR-584-5p expression, reduced AFP levels, and significantly slowed tumor growth in HCC." (PMID 33292243, 2020). "Compared with the patients in the low-Fb score group, those in the high-Fb score group were mostly single and male and were more likely to have higher AFP levels, small tumor size (≤3 cm), and multiple tumors." (PMID 32539768, 2020). "So far, studies on the biological significance of AFP have focused on the effect of circulating AFP on tumour development." (PMID 33090723, 2020). "Univariate Cox regression analysis showed that tumor number (P < 0.01), AFP level (P < 0.05), TNM stage (P < 0.05), and venous invasion (P < 0.001) were independent prognostic factors for HCC patients." (PMID 32382531, 2020). "We found that tumor size and number, BCLC stage, tumor capsule, ALB, AST, ALT, and AFP levels were related to the risk of all-cause mortality." (PMID 33505912, 2020). "In other studies, however, serum miR-21 proved to be an independent predictor for tumor recurrence following treatment, stronger than AFP, raising important physiopathological questions." (PMID 32793278, 2020). "It was widely proved that macrovascular and microvascular invasion, high AFP level before LT, as well as poor tumor differentiation are the most important factors affecting HCC recurrence." (PMID 33365268, 2020). "As expected, the proportions of patients with multiple tumors, tumor size> 5 cm, and AFP > 200 ng/dL were higher in the MVI or EHS subgroup." (PMID 32163475, 2020). "Tumor size, AFP, AFP-L3, and DCP values were significantly higher in the 18F-FDG-PET positive group than the negative group." (PMID 33076990, 2020). "The inverse relation between AFP serum levels and tumour volume or response to cisplatin treatment in both PDX models suggests that AFP should not be used as response evaluation tool in TC PDX models." (PMID 33144587, 2020). "These baseline factors included age, gender, AST and ALT levels, platelet counts, HBeAg status, HBV DNA level, AFP level, Child classification, tumor size and the BCLC stage." (PMID 32330203, 2020). "We further analyzed the 12-month OS in HCC patients with AFP <400 ng/ml or AFP ≥400 ng/ml, tumor number <3 or tumor number ≥3, and tumor diameter <5 cm or tumor diameter ≥5 cm who underwent TACE + RFA or TACE alone." (PMID 32884569, 2020). "This work has highlighted the limitations of currently used tumor markers, namely AFP, β-hCG, and LDH." (PMID 32235691, 2020). "In accordance with the HAP score, it contained the parameters albumin (< 36 g/dl) and bilirubin (> 17 μmol/l) for liver function, AFP (> 400 ng/dl) and tumour size (> 7 cm) for tumour burden and additionally rated the lesion number (≥ two)." (PMID 32125515, 2020). "Lower tumor differentiation grades, higher alpha-fetoprotein level, bigger tumor size, and higher tumor extension were all significantly correlated with poor prognosis." (PMID 32117759, 2020). "The coexistence with chronic liver disease and inflammation has counterbalanced the accuracy of several tumor biomarkers, precluding them to be widely use in daily practice, except for AFP." (PMID 32492896, 2020). "On univariate analysis, the following six variables were associated with poor RFS: elevated PIVKA-II (P = 0,048), elevated α-fetoprotein (AFP) (P = 0.036), tumor number (P = 0.025), IM (P < 0.001), Vp (P = 0.016), and blood transfusion (P = 0.008)." (PMID 33028209, 2020). "By comparing the ROC curve features and AUCs, the results showed that compared with AFP, tumor diameter and CTC, the multiparameter combination had the most significant power for predicting the presence of MVI." (PMID 33129301, 2020).
tumor (continued). "Elevation of serum tumor markers such as alpha-feto protein (AFP), carcinoembryonic antigens (CEA), human chorionic gonadotropin (HCG) and lactate dehydrogenase (LDH) are usually suggestive of malignant transformation." (PMID 33234106, 2020). "Ninety-three HBV-related HCC patients in the TCGA dataset with complete information, including gender, age, AFP, stage, tumor grade, alcohol consumption, and new tumor events, were included for further analysis." (PMID 32552682, 2020). "The baseline characteristics of the patients, including sex, age, HBsAg(+), tumor size, tumor number, Child-Pugh class and AFP, were homogeneous." (PMID 33246417, 2020). "TACE + RFA provides a superior survival outcome than TACE alone in HCC patients, especially in AFP <400 ng/ml, tumor <3, tumor diameter <5 cm, or PVTT group." (PMID 32884569, 2020). "Univariable analyses of OS revealed that in the LSG the following factors were prognostically significant: resection type, ICGR15, AFP, PIVKA2, tumor size, operation time, blood loss, HBV, hepatic vein invasion, and portal vein invasion." (PMID 33272298, 2020). "Among the eight gene modules, brown and turquoise modules were closely related to clinical characteristics, such as primary tumor size, AFP level, TNM stage, and overall survival time." (PMID 33133125, 2020). "A significant inhibition of HCC occurrence and the suppression of the tumor marker of AFP and des-gamma-carboxy prothrombin can be seen in mice groups treated with hydrodynamic gene delivery of DTA, both 0 and 2 months after the YAP gene delivery." (PMID 32085552, 2020). "Intriguingly, the low ACADL expression group had increased serum AFP levels (P = 0.01), larger tumor size (P = 0.036), promoted vascular invasion (P = 0.004), and recurrence (P = 0.002)." (PMID 32219176, 2020). "In a phase II placebo-controlled randomized discontinuation study, cabozantinib suppressed tumor growth, disease stability and reduced alpha fetoprotein (AFP) in HCC." (PMID 33195182, 2020). "Actually, the levels of AFP rapidly declined following the surgical treatment with both tumor markers falling within normal range, which was in agreement with the clinical observations of no recurrence in our patient." (PMID 32769926, 2020). "The recommended noninvasive methods include imaging techniques such as magnetic resonance imaging and the use of tumor markers such as AFP." (PMID 31821607, 2020). "HCC diagnosis and surveillance are mostly based on the detection of tumor markers, such as alpha-fetoprotein (AFP) and protein induced by vitamin K absence or antagonist-II (PIVKA-II), and imaging techniques." (PMID 32023902, 2020). "By relative quantifying the intact N-glycopeptides between low and high AFP tumor groups, the great heterogeneities of site-specific N-glycans between two groups of HCC tumors were also uncovered." (PMID 32426269, 2020). "Multivariate Cox regression analysis showed that high AFP level and tumor embolus were independent prognostic factors for patients with HCC." (PMID 33289700, 2020). "All of them have highlighted the importance of tumor activity markers such as tumor size, tumor focality, and alpha-fetoprotein." (PMID 33202588, 2020). "Depending on the tumor stage and size, AFP-positive patients (>40 ng/mL) were increased although at a low level (20~40%)." (PMID 33352757, 2020). "The criteria in this study included the up-to-seven criteria, which include tumor number and size, albumin concentration as a measure of liver function, and tumor marker (AFP) as malignant potential." (PMID 33112547, 2020). "We also build a predicted model of MVI based on the patients in our study, which included ALP, AFP, PT, and tumor capsule." (PMID 32478080, 2020). "High levels of expression of NF90-Ser382 phosphorylation were remarkably correlated with large tumor size (p < 0.0026) and high AFP levels (p < 0.0037)." (PMID 32123579, 2020).
tumor (continued). "Both FRP and GPR significantly increased with the progression of AFP-NHCC as well as tumor size and cancer stage." (PMID 32190001, 2020). "The tumor markers alpha-fetoprotein (AFP), L3 isoform of AFP (AFP-L3), and DCP were followed before, immediately after, and three months after radiotherapy." (PMID 33066141, 2020). "We found that variables reflecting tumor aggressiveness were the only independent predictors of IDR occurrence: AFP >100 ng/mL (3-fold increased risk of IDR) and tumor size (IDR risk increased by 6% per mm of tumor diameter increase)." (PMID 32013112, 2020). "In this regard, since 2013, France has adopted the AFP model, which includes AFP values and radiological tumor burden, as a selection tool for transplant candidates." (PMID 32492896, 2020). "In clinical practice of TGCTs, the three common tumor markers including Alpha‐fetoprotein (AFP), b‐human chorionic gonadotrophin (b‐HCG), and lactate dehydrogenase (LDH), are used for diagnosis, risk assessment, and determining patient prognosis." (PMID 33034957, 2020). "AFP is a known tumor marker for HCC, and it has been reported to correlate with tumor diameter and differentiation of HCC." (PMID 32928172, 2020). "The monitoring of disease course and recurrence is supported by traditional tumor markers, including α-fetoprotein (AFP)." (PMID 31906360, 2020). "We further assessed the association of highly mutated genes with different clinical parameters, including BCLC stage, gender, AFP, age, vascular invasion, and tumor size, in HBV‐related HCC." (PMID 32017470, 2020). "The levels were associated with age (p = 0.001), BCLC stage (p < 0.001), levels of AFP (p < 0.001), tumor size (p < 0.001), tumor number (p < 0.001), PVTT (p < 0.001), EHM (p < 0.001) and Child-Pugh stage in the HCC cohort." (PMID 31898536, 2020). "Univariable analysis of RFS revealed that in the LSG the following factors were prognostically significant: resection type, ICGR15, AFP, PIVKA2, tumor size, operation time, blood loss, HBV, hepatic vein invasion, and portal vein invasion." (PMID 33272298, 2020). "There were 3,211 people with tumours greater than or equal to 3 cm and 2,555 people were AFP positive." (PMID 32117619, 2020). "As no significant heterogeneity between studies was found, fixed-effect models were used except tumor size and serum AFP level." (PMID 32214401, 2020). "Seven prognostic factors were identified and integrated to establish a novel prognostic nomogram, which included tumor size, microvascular invasion, tumor differentiation, Ki67 (%), α-fetoprotein (AFP), carbohydrate antigen 125 (CA125), and HBsAg status." (PMID 33312945, 2020). "The largest weighted factor in the MoRAL-AI model was maximum tumor diameter, followed by AFP, age, and PIVKA-II." (PMID 33003306, 2020). "This is associated with clinical pathologic features such as HBsAg positivity, tumor size, or AFP levels." (PMID 32443747, 2020). "The univariate analysis determined a significant influence of the AFP level, number of tumors, maximum diameter of the largest tumor, and tumor grade on the outcome after LTx." (PMID 32635931, 2020). "Factors that were associated with early recurrence, defined as within 2 years after therapy, included tumor multi-nodularity, presence of microvascular invasion, and elevated serum alpha-fetoprotein." (PMID 32718047, 2020). "The present study showed that AFP, PLR, largest tumor size, MVI and the radiomics signature were independent risk factors for OS." (PMID 33198809, 2020). "In summary, we established a diagnostic panel consisting of serum lncRNA linc00152, UCA1, and tumor marker AFP with superior sensitivity and specificity to diagnose HCC." (PMID 32733618, 2020). "AFP, tumor diameter and preoperative CTC count were included in the model to predict the presence of MVI." (PMID 33129301, 2020). "Consider omitting radiology response assessment and continue to clinical progression according to tolerance and tumour marker alpha-fetoprotein." (PMID 32565901, 2020).